HIF1A (hypoxia inducible factor 1 subunit alpha)
Diseases named in the same sentence as HIF1A in open-access papers (continued):
Sharing a sentence is not in itself a finding about the gene and the disease.
breast cancer (continued). "In hypoxic breast cancer, ERα is degraded via the proteasomal pathway which is dependent on the interaction between HIF-1α and the ERα." (PMID 39282472, 2024). "Overexpression of miR-181c drives the impairment in activation of HIF-1α/BNIP3-mediated autophagy in Nrf2-silenced breast cancer cells." (PMID 38970040, 2024). "HSP90 inhibitor AT-533 has been reported to inhibit growth and angiogenesis by suppressing the HIF-1α/VEGF pathway in hypoxic breast cancer cells." (PMID 39148727, 2024). "Recent studies have shown that the NF-κB, RAS-RAF-MEK-ERK, PI3K/Akt/mTOR, and JAK-STAT signaling pathways regulate the expression of HIF-1α, which in turn drives the biological processes of breast cancer cell proliferation, angiogenesis, and BCSCs enrichment." (PMID 38236337, 2024). "A study registered under ClinicalTrials.gov ID NCT01763931 investigated the pharmacodynamics of IG-HIF1 in breast cancer, revealing insights into HIF1α’s role in predicting tamoxifen resistance." (PMID 39697237, 2024). "It has been shown to induce apoptosis in breast- and lung- cancer cells by downregulating the TGF-β/ERK signaling pathway and reversing the EMT process in breast cancer by inhibiting the HIF-1α pathway." (PMID 39519238, 2024). "All three radiotracers showed similar uptake in the hypoxic regions of the two breast cancer models being correlated with elevated levels of HIF-1α expression; additionally, 18F-FBNA showed higher tissue clearance compared to 18F-MISO." (PMID 38920676, 2024). "In VEGFR2-luc transgenic mice implanted with breast cancer cells, miR-21 knock-down impaired angiogenesis by suppressing the HIF-1α/VEGF/VEGFR2 pathway." (PMID 39063226, 2024). "HIF-1α induces VEGFA production by both breast cancer stroma and tumor-associated macrophages, which make up ~50% of the total cellular mass in breast cancers." (PMID 39439572, 2024). "This research successfully profiled the metabolites of Seagrass Enhalus acoroides through both in silico and in vitro studies, revealing its ability to combat breast cancer by inhibiting HIF-1α, EGFR tyrosine kinase, and HER2 through molecular docking." (PMID 38474594, 2024). "It is anticipated that the future will see the introduction of effective HIF-1α inhibitors into clinical trials, offering new hope for breast cancer patients." (PMID 38799423, 2024). "FVB mice harboring Hif-1α knockout mammary tumor epithelial cells displayed reduced tumor growth, reduced lung metastasis and increased survival compared to wild type cells." (PMID 39253073, 2024). "In this study, our data corroborate the role of miR-622 in facilitating miR-30a transcription, consequently counteracting breast cancer cell metastasis through suppression of HIF-1α expression." (PMID 38339408, 2024). "Upregulation of HIF-1α by either hypoxia or bandalit (MCT4 inhibitor) decreased ERα positive breast cancer cell line sensitivity to tamoxifen." (PMID 39282472, 2024). "This study identified HIF1A as a prominent metastasis target in OSCC metastasized from breast cancer, with isonahocol D2 showing strong binding affinity and favorable pharmacokinetic properties." (PMID 39458948, 2024). "In breast cancer, HIF-1α's regulation of these processes is particularly critical, influencing tumor aggressiveness, therapeutic resistance, and overall prognosis." (PMID 38842687, 2024). "LncRNA DLEU1 (deleted in lymphocytic leukemia 1) acts as the coactivator for hypoxia inducible factor 1 subunit alpha (HIF-1α) to induce expression of cytoskeleton associated protein 2 (CKAP2) and consequently pro-tumor activities in breast cancer." (PMID 39346726, 2024). "Antiangiogenic agents, such as bevacizumab, induce CSC enrichment in breast cancer xenografts by creating an intratumoral hypoxic environment and upregulating HIF-1α expression." (PMID 38424190, 2024). "Under hypoxic conditions (2% O2), miR-18a inhibits the expression of HIF-1α, which in turn suppresses lung metastasis in breast cancer MCF7 cells." (PMID 38766303, 2024).
breast cancer (continued). "Here, JMJD2C removes H3K9me3 marks and enhances the binding of HIF-1α leading to enhanced expression of key genes required for breast cancer progression (PDK1) and metastasis to the lung (LOXL2 and L1CAM)." (PMID 39282472, 2024). "In breast cancer cells, hypoxia increased circSTT3A (has_circ_0024760) in a HIF-1α-dependent manner; circSTT3A directly bound with the HSP70 protein to recruit and stabilize PGK1." (PMID 38730681, 2024). "An in-silico study revealed its ability to combat breast cancer by inhibiting the HER2/EGFR/HIF-1α pathway through molecular docking." (PMID 38474594, 2024). "Meanwhile, PDK1 knockdown reduced the proliferation, migration, and tumorigenicity of breast cancer cells and inhibited the HIF-1α signaling pathway." (PMID 39199957, 2024). "Subsequently, correlation analysis of breast cancer in TCGA indicated that the expression of CARM1 is positively correlated with that of HIF1A and CDK4." (PMID 38476024, 2024). "This study’s results emphasized that isonahocol D2 is a promising therapeutic candidate against HIF1A in OSCC metastasized from breast cancer in translational medicine." (PMID 39458948, 2024). "A liposomal nano-formulation delivering the Fenton’s catalyst, copper oleate, and the HIF-1 inhibitor, acridinium flavonoids (ACF), has been reported to be useful for breast cancer treatment, which further emphasizes the role of HIF-1α in the regulation of BC." (PMID 39027328, 2024). "LDHA knockdown also destabilizes HIF1α to promote immune cell infiltration, improving immunotherapy outcomes in murine breast cancer." (PMID 38715072, 2024). "Hypoxia inducible factor-1α (HIF-1α) was reported to play an important role in breast cancer metastasis." (PMID 38167685, 2024). "Regulation of a miR-18a-mediated hypoxic gene signature by activation of HIF-1α in basal breast cancer has been reported previously." (PMID 38786043, 2024). "Under hypoxic conditions, HIF-1A was upregulated in breast cancer cells, and overexpression of some miRNAs such as miR-497 and miR-7641 can suppress this gene." (PMID 38462658, 2024). "This article elaborates on the structure and function of HIF-1α, its mechanism of action in developing breast cancer, and drug resistance mechanisms." (PMID 38799423, 2024). "This conclusion followed the observation that the genetic depletion of Mcl-1 lowered both HER2 and HIF-1α levels, hindering the survival of breast cancer cells." (PMID 38920676, 2024). "MicroRnma 18a (miRNA-18a) expression is suppressed in breast cancer cells that spontaneously colonise the lungs, likely through the direct activation of HIF-1α." (PMID 39282472, 2024). "We identified a novel role and regulatory mechanism of the PDK1/HIF-1α positive feedback loop in breast cancer, which provides a promising strategy for breast cancer treatment." (PMID 38560503, 2024). "For instance, in breast cancer and head and neck tumour cells, hypoxia-induced HIF-1α interacts with the hypoxia-inducible element (HRE) of LOX, thereby enhancing the transcription and expression of LOX." (PMID 39247609, 2024). "This current research underscores the potential of miR-622 to inhibit metastasis in breast cancer cells by targeting HIF-1α, counteracting mesenchymal proteins." (PMID 38339408, 2024). "Several studies have identified Nrf2 and HIF-1α signaling pathways as important targets for breast cancer radioresistance." (PMID 38993643, 2024). "Collectively, these findings indicate that miR-622 plays a crucial role in promoting miR-30a production, thus reversing breast cancer cell metastasis through suppression of HIF-1α expression." (PMID 38339408, 2024). "The focus of this study is to investigate the regulatory mechanism of UBE2M expression in ER+ breast cancer, which is mediated by HIF-1α." (PMID 39138151, 2024). "HIF-1α inhibits Rad51 and induces DNA breaks in early-stage breast cancer cells, notably in breast tumor-initiating cells (BTICs) by targeting EZH2." (PMID 38911968, 2024).
breast cancer (continued). "HIF activation, particularly the stabilization of HIF-1α under hypoxic conditions, is a key mechanism contributing to the dysregulated metabolism of cancer cells, including breast cancer." (PMID 39408832, 2024). "Our study demonstrates that miR-622 can modulate the expression levels of beclin 1-dependent genes, altering cancer progression and reinstating drug sensitivity by suppressing HIF-1α expression in breast cancer cells." (PMID 38339408, 2024). "Previously, we have reported that TGBR2, PI3K, SRC, FAK, and HIF1-α were direct targets of miR-204 in breast cancer cells." (PMID 38392969, 2024). "This effort is crucial to comprehensively elucidate the regulatory dynamics at play and to advance our understanding of the interaction between miR-622, miR-30a, and HIF-1α in breast cancer metastasis." (PMID 38339408, 2024). "circRNF20 can promote breast cancer cell proliferation and aerobic glycolysis through the circRNF20/miR-487a/HIF-1α/HK2 axis." (PMID 38408962, 2024). "While many direct inhibitors of HIF-1α have shown promising results in preclinical studies, comprehensive breast cancer clinical trials are still needed." (PMID 39253073, 2024). "Kaplan-Meier analysis revealed that ER+ breast cancer patients with high HIF-1α expression had a worse prognosis compared to those with low HIF-1α expression; while, in ER- breast cancer patients, HIF-1α expression was weakly associated with prognosis." (PMID 39138151, 2024). "In this study, we found that DAB2IP inhibited glucose uptake under hypoxia conditions in breast cancer cells by suppressing HIF-1α signals." (PMID 38862467, 2024). "Hormone signalling, particularly through ERα, is also tightly regulated by hypoxic exposure, with HIF-1α expression being a prognostic marker for therapeutic resistance in ER+ breast cancers." (PMID 39282472, 2024). "We evaluated the relative expression levels of endogenous miR-622 transcripts and HIF-1α protein in various breast cancer cell lines using qRT-PCR and Western blot techniques, respectively." (PMID 38339408, 2024). "This review also summarizes strategies to overcome HIF-1α-dependent drug resistance and the current status of targeted HIF-1α therapy for breast cancer." (PMID 38799423, 2024). "Collectively, these findings suggested that PHF6 coordinates HIF1α/HIF-2α to bind to HIF downstream targets in breast cancer cells." (PMID 36967443, 2023). "A recent report proposed that SETD5 regulates glycolysis through the regulation of EP300/HIF-1a co-activators upon the hypoxic condition in breast cancer stem-like cells." (PMID 37264456, 2023). "ERβ1 has previously been shown to inhibit HIF-1α expression in both breast cancer and prostate cancer." (PMID 36982940, 2023). "LncRNAs such as lymphocytic leukemia 1 (DLEU1) are associated with breast cancer and up-regulate CKAP2 expression to promote breast cancer malignancy via serving as a co-activator of HIF-1α." (PMID 36597032, 2023). "The analyses of CTCs from metastatic breast cancer patients have consistently shown high levels of HIF1α expression, though levels of CTC-CAIX have yet to be studied." (PMID 36979915, 2023). "DPP-4 knockdown significantly promoted the levels of CXCL12, CXCR4, phospho-mTOR, and HIF-1α in breast cancer cell lines." (PMID 37760498, 2023). "Immunoblotting showed that hypoxia significantly increased HIF‐1α protein expression level in the seven breast cancer cell lines." (PMID 36757143, 2023). "Doxorubicin-metformin liposomes inhibit HIF-1α and tumor growth in multiresistant breast cancer cells, suggesting that this combination has the potential to revert HIF-1α-induced treatment resistance." (PMID 37460927, 2023). "CircRBM33 and circZFR, as sponges of miR-542-3p, upregulate HIF-1α, accelerate the glycolysis of breast cancer cells, and promote the proliferation and metastasis of breast cancer cells." (PMID 37204526, 2023).
breast cancer (continued). "It was found that HIF1α contributes to poor prognosis and tamoxifen resistance in breast cancer, and that its inhibition can restore tamoxifen sensitivity." (PMID 36869202, 2023). "STAT3/HIF-1α signaling pathway inhibition can attenuate the resistance of breast cancer cells to adriamycin." (PMID 37628777, 2023). "FBXW7 liberation from C/EBPδ transcriptional repression promotes polyubiquitination of endogenous mTOR and HIF-1α protein binding and inhibits intracellular accumulation, reducing lung metastasis in breast cancer model mice under hypoxic adaptation." (PMID 37658431, 2023). "HIF-1α and IL-6Rα overexpression in breast cancer patient sera creates a hypoxic environment and abnormal inflammation in tumor cells, promoting metastasis." (PMID 37658431, 2023). "Breast cancer cells induce the expression of cytokines (CCL2, CCL5, IL-1β, and IL-6) and immunomodulators (COX2, HIF-1α, VEGFα, and PD-L1) by cancer-associated adipocytes." (PMID 36670988, 2023). "Here, we report breast cancer cell-secreted exosomal miR-204-5p induces hypoxia-inducible factor 1A (HIF1A) in WAT by targeting von Hippel-Lindau (VHL) gene." (PMID 37620316, 2023). "Under these conditions, detection of HIF1α in plasma circulating sEVs was feasible by Western blotting and correlated with clinical recurrence in all luminal breast cancer patients examined, up to 103 months after initial diagnosis." (PMID 36892943, 2023). "The E‐cadhesion formation, HIF‐1α‐mediated senescence decrease, and tumor stemness enhancement can drive drug resistance and antitumor drug screening of breast cancer cells." (PMID 37424037, 2023). "Our findings identify a novel role for DPP-4 inhibition in the promotion of breast cancer survival by inducing CXCL12/CXCR4/mTOR/HIF-1α axis-dependent autophagy." (PMID 37760498, 2023). "HIF-1α expression was recently correlated with radiotherapy response in breast cancer, oropharyngeal cancer, head and neck cancer, early esophageal cancer, and nasopharyngeal carcinomas or cervical cancer." (PMID 37296922, 2023). "HIF-1α overexpression correlates with poor prognosis in triple-negative breast cancer (TNBC), including familial-associated breast cancer." (PMID 36831687, 2023). "Vascular endothelial growth factor (VEGF) is a downstream target gene of HIF1α, which increases angiogenesis and invasiveness of breast cancer cells." (PMID 36869202, 2023). "Among HIF1α responsive genes, there are several members involved in tumor growth, angiogenesis, and survival, and it has been demonstrated that in breast cancer cells, HIF1α directly regulates SCF gene expression also as a response to EGF." (PMID 37686233, 2023). "In this study, we initially found the important roles of PI3K/AKT signaling and HIF1α in calcified breast cancer cells." (PMID 37957150, 2023). "The transcriptome of sEV-induced mammary gland lesions resembled luminal breast cancer, and detection of HIF1α in plasma circulating sEVs from luminal breast cancer patients correlated with disease recurrence." (PMID 36892943, 2023). "It has been shown that HOIL-1 interacts with the HIF1α protein to indirectly inhibit its polyubiquitination and degradation, thereby promoting HIF1α-targeted gene expression as well as breast cancer progression." (PMID 38017534, 2023). "Multiple lines of evidence have proved that the HIF1α pathway is vital for glioma angiogenesis, and sensors associated with IRE1α and XBP1 have been reported to be involved in the regulation of HIF1α pathway in breast cancer." (PMID 36997943, 2023). "HIF1α is also capable of indirectly inducing FASN expression by activating sterol regulatory element binding protein 1 (SREBP1) in breast cancer cells." (PMID 37627128, 2023). "In view of reducing Doxo side effects, which is of great importance in breast cancer treatment, this finding supports the possibility to combine Doxo with other drugs acting on HIF-1α or CMA." (PMID 37407979, 2023).
breast cancer (continued). "Other studies suggest that HIF-1α induces the metabolic reprogramming of CAFs and increases glycolysis, thereby promoting tumor growth in breast cancer." (PMID 36768815, 2023). "In conclusion, we show here that DPP-4 inhibition accelerates breast cancer cell survival by inducing autophagy through CXCL12/CXCR4-mediated mTOR/HIF-1α activation; metformin abrogates such alterations induced by DPP-4 suppression." (PMID 37760498, 2023). "DPP-4 knockdown and DPP-4 inhibitor KR62436 (KR) treatment both increased the levels of LC3II and HIF-1α in cultured human breast and mouse mammary cancer cells." (PMID 37760498, 2023). "USP22 positively regulates c-Myc, androgen receptor, and HIF-1α actions to promote breast cancer, prostate cancer, and HCC progression." (PMID 36906615, 2023). "Meanwhile, calcified breast cancer cells restored sensitivity to doxorubicin because of suppressed HIF1α expression." (PMID 37957150, 2023). "After 3 days of cultivation in the PAC system, tumor slices of MCF-7 xenografts, a breast cancer model, showed similar morphology and biomarker expression (ER, HIF1α, Ki67, and γH2AX) to the original tissues." (PMID 36899943, 2023). "Consistent with this view, detection of HIF1α in plasma circulating sEVs was feasible and predicted luminal breast cancer recurrence in a small, proof-of-concept patient series, up to 103 months after diagnosis." (PMID 36892943, 2023). "Mechanistically, both local and systemic aspects of sEVHYP signaling are mediated by HIF1α, which is packaged in sEVHYP and predicts clinical recurrence in luminal breast cancer patients." (PMID 36892943, 2023). "CLDN6 expression in breast cancer is regulated by transcription factors such as HIF-1a, FoxA2, Gata6, and TTF-1 at the claudin 6 promoter." (PMID 37762277, 2023). "Overexpression of MYC significantly stabilizes HIF1A and enhances HIF1A accumulation under both normoxic and hypoxic conditions in human normal immortalized mammary epithelial cells and breast cancer cells." (PMID 37998757, 2023). "We demonstrate that MBZ can inhibit the transcriptional activity of HIFs in breast cancer cell lines and in preclinical models of breast cancer by preventing the induction of HIF-1α, HIF-2α, and HIF-1β at the protein level under hypoxic conditions." (PMID 36831670, 2023). "Overexpression of HIF‐1α has been positively correlated with poor prognosis and disease progression in many studies on patients with breast cancer." (PMID 36757143, 2023). "DPP-4 suppression augmented CXCL12/CXCR4 levels, which led to autophagy and HIF-1α in breast cancer cells; a CXCR4 inhibitor reversed these DPP-4 inhibition-induced alterations." (PMID 37760498, 2023). "In breast cancer, HIF-1α enhanced the expression of COX-2 and induced PGE2 to activate vascular endothelial cells in a paracrine manner." (PMID 36702852, 2023). "Recently, ALKBH5 was shown to be directly targeted by HIF1α and regulated by HIF2α in breast cancer cells." (PMID 37149664, 2023). "In breast cancer, proline released by prolidase was found to regulate HIF-1α expression and stimulate autophagy." (PMID 37745688, 2023). "HIF-1α has been positively correlated with HK2 expression in breast cancer tissues, and bioinformatics analysis has shown that HIF-1α has a hypoxic response element (HRE) in the upstream promoter region of HK2." (PMID 36793034, 2023). "Stable downregulation of HIF-1α has been shown to reverse chemotherapy resistance, inhibit proliferation, migration, and invasion of cancer cells, and slow down the tumor growth in breast cancer xenograft models." (PMID 36982940, 2023). "Another study also demonstrated the existence of the positive feedback mechanism between the lactic acid production and HIF-1α/STAT3 axis to promote tamoxifen‐resistant breast cancer cells." (PMID 37900137, 2023). "One such example is lncRNA BCRT1, whose expression is strongly induced in breast cancer cells as a response to hypoxia through HIF-1α-dependent transcriptional regulation." (PMID 35842651, 2022).